MYD88 (MYD88 innate immune signal transduction adaptor)
Diseases named in the same sentence as MYD88 in open-access papers (continued):
Sharing a sentence is not in itself a finding about the gene and the disease.
bladder cancer (5 papers, 2020 to 2022). "As a TLR4/2 agonist, BCG mediates MyD88-dependent innate immune response in the tumor microenvironment, contributing to the therapy of bladder cancer." (PMID 36119107, 2022). "For example, inhibition of MYD88 induces apoptosis in both triple negative breast cancer and bladder cancer." (PMID 32730293, 2020). "Previously, these BCG-derived products (BCG-CWS or BCG-derived DNA/RNA) were found to induce apoptosis in bladder cancer cells by activating TLR2, TLR4, TLR7, and TLR9 and thus inducing the myeloid differentiation primary response gene 88 (MYD88) pathway of extrinsic apoptosis." (PMID 36248858, 2022). "In summary, our report suggests the involvement of MyD88 and not a single TLR tested here in BCG immunotherapy against bladder cancer." (PMID 34341449, 2021). "However, it is not known if BCG, like LPS, activates MyD88 to stabilize IAP proteins in bladder cancer cells and if the subsequent increase of IAP proteins contributes to the failure of BCG in treating some cases of bladder cancer." (PMID 36119107, 2022).
breast DLBCL (5 papers, 2017 to 2025). "To date, mutations in MYD88 have been implicated in primary breast DLBCL, primary renal lymphoma, central nervous system DLBCL, and primary testicular lymphoma." (PMID 39273276, 2024).
co-infection (5 papers, 2014 to 2023). "RSV infection of MDDC caused MyD88-independent STAT1 phosphorylation, whereas BPZE1 activated MyD88-dependent signaling pathways; co-infection caused both pathways to be activated." (PMID 24967823, 2014). "We recently reported that in HIV-M. tuberculosis co-infection, IL-27 is expressed by myeloid-derived suppressor cells with diminished MyD88 gene expression." (PMID 36863206, 2023). "Co-infection of MyD88 knockout mice with H. polygyrus results in the development of more severe disease, more significant and prolonged body weight loss during the course of the experiment." (PMID 25010669, 2014). "In contrast, a marked increase in bacterial translocation was detected in MyD88 knockout mice with helminth-coinfection, evidenced by detection of significantly increased distribution of GFP-C." (PMID 25010669, 2014). "Our results further show that H. polygyrus co-infection suppresses bacterial induced KC response in both wild-type and MyD88 knockout mice and that, in fact, such response is completely abolished in MyD88 knockout mice." (PMID 25010669, 2014). "Also, PDCoV/PEDV co-infection has induced a higher up-regulatory effect on MyD88 and TRIF by 3 DPI as compared with single-PDCoV or PEDV infection." (PMID 36376395, 2022). "Furthermore, co-infection of MyD88 knockout mice results in a significant increase in mortality that occurred as early as 3 days after C. rodentium infection compared to MyD88 knockout mice with C. rodentium infection alone." (PMID 25010669, 2014). "Therefore, MyD88-dependent mechanisms are required to protect against Citrobacter infection, particularly in the context of H. polygyrus co-infection." (PMID 25010669, 2014). "Our results further show that an intestinal helminth co-infection results in the development of more pronounced damage in colon of MyD88 knockout mice than that observed in MyD88 knockout infected with C. rodentium alone or in WT mice with C. rodentium alone or co-infection." (PMID 25010669, 2014). "Moreover, examination of fecal bacterial output suggests that helminth co-infection results in significantly increased bacterial shedding in MyD88 knockout mice." (PMID 25010669, 2014). "In addition, a markedly reduced distribution and frequency of colonic CD11b+ macrophages in MyD88 knockout during bacterial infection as well as co-infection may contribute to reduced production of KC and MIP-2." (PMID 25010669, 2014). "Furthermore, during co-infection, Wolbachia appeared also to dampen the immune induction by JCV at some time points (see AGO, vago, and hop, as well as MYD88 and IMD at 3 dpi) suggesting immune activation is unlikely to be at play here." (PMID 37669272, 2023). "The results suggest that co-infection with intestinal nematode parasite negatively regulates intestinal recruitment of mononuclear phagocytes and neutrophils, which is correlated with significant reduction of colonic chemokine expression in mice, particularly those lacking MyD88 signaling." (PMID 25010669, 2014). "At necropsy, the colons from the different groups (C. rodentium alone, H. polygyrus alone, co-infection, and non-infected controls) of wild type C57BL6 and MyD88 knockout mice were examined both macroscopically and microscopically." (PMID 25010669, 2014).
cognitive decline (5 papers, 2016 to 2026). "The positive effects are involved in the participation of the irisin/TLR4/MyD88/NF-κB signaling pathway, highlighting the potential of exercise in the management of diabetic-induced cognitive decline." (PMID 39452118, 2024). "Our previous studies found that microglia activation participate in the surgery-induced neuroinflammation and cognitive decline through TLR4/MyD88 signaling, which can be improved by preintraperitoneal injection of lithium for continuous 6 days before splenectomy." (PMID 27245661, 2016). "Conversely, TLR4 KO can counteract the B2M-induced cognitive decline due to neuroinflammation and apoptosis via a modulation of hippocmapal neurogenesis, synaptic plasticity through TLR4/MyD88/NF-κB signaling pathway." (PMID 32059688, 2020).
coronary artery disease (5 papers, 2016 to 2025). "The toll-like receptor 4 (TLR4)-myeloid differentiation factor 88 (MyD88)-dependent signaling pathway plays a role in the initiation and progression of coronary artery disease (CAD)." (PMID 26959040, 2016). "By demonstrating its efficacy in ameliorating dysfunction, inflammation, and fibrosis post-AMI via targeted inhibition of the TLR4/MyD88/NF-κB pathway, this study validates its traditional use and offers a compelling candidate for targeted treatment of ischemic heart disease." (PMID 41155364, 2025).
diabetic retinopathy (5 papers, 2013 to 2023). "Further studies on the association of miR-146a with TLR4 and MyD88 pathways will broaden our understanding on the regulation of retinal endothelial permeability and contribute to developing novel therapeutic strategies for the complications of diabetic retinopathy." (PMID 26997759, 2016). "Additional studies will be required to more fully assess the suitability of targeting of MyD88 to inhibit diabetic retinopathy." (PMID 23874797, 2013). "If inhibition of MyD88 is to be considered as a therapy for diabetic retinopathy, the balance of these multiple effects of MyD88 will need to be further evaluated." (PMID 23874797, 2013). "Since most of them were shown to be MyD88-dependent, we thus postulate that MyD88-dependent pathways (and presumably the innate immune system) are important in the development of metabolic and physiologic abnormalities that contribute to diabetic retinopathy." (PMID 23874797, 2013). "Moreover, NE stimulates retinal vascular leakage during progression of diabetic retinopathy in a murine model most likely via the activation of myeloid differentiation primary response 88 (MyD88), NF-κB, and PAR2 as well as degradation of vascular endothelial cadherin." (PMID 34869231, 2021). "The potential contributions of TLRs and MyD88-dependent processes in development of the molecular and physiological abnormalities that contribute to diabetic retinopathy have not been previously studied." (PMID 23874797, 2013). "A variety of physiologic abnormalities that have been implicated in the pathogenesis of diabetic retinopathy failed to develop in retinas of diabetics lacking TLR2/4, further implicating the TLR/MyD88 system in the pathogenesis of diabetic retinopathy." (PMID 23874797, 2013).
emphysema (5 papers, 2013 to 2023). "To further explore the requirement for Mal in lung pathology, we assessed its role in two cellular mechanisms, apoptosis and oxidative stress, which are associated with emphysema in Tlr4−/− (and MyD88−/−) mice." (PMID 24205107, 2013). "In particular, upregulation of MMP-1 expression can be involved in the progression of emphysema by regulating the MyD88/IRAK1 signalling pathway." (PMID 35388750, 2023). "Precisely how TLR7 signaling and MyD88 activation regulate mast cell function to drive emphysema and COPD remain to be determined in future studies." (PMID 37963864, 2023). "With regard to MyD88, it serves as an essential adaptor protein in TLR and IL1R signaling pathway, and MyD88 deficiency leads to spontaneous emphysema." (PMID 25962837, 2015). "Since it has also been shown that MyD88 (like TLR4) is required to prevent the onset of emphysema, these observations reveal a differential requirement for Mal and MyD88 in maintaining normal lung architecture via TLR4 signaling." (PMID 24205107, 2013). "It remains unknown exactly why TLR7 increased and how TLR7, MyD88, and mMCP-6/hTrypase-β induce degranulation and emphysema and these mechanisms need to be defined." (PMID 37963864, 2023). "CS-related TLR4 signaling was shown to increase MMP-1, a crucial actor in emphysema, in a MyD88- and IRAK1-dependent manner, while CS-exposed TLR4–/– mice were protected from emphysema, impaired lung function, airway fibrosis, and collagen deposition in small airways as compared with wild-type mice." (PMID 34248677, 2021). "While genetic ablation of the TLR4/MyD88 signaling axis in mice leads to pulmonary cell death and oxidative stress culminating in emphysema, the involvement of Mal, as well as TLR2 which like TLR4 also signals via MyD88 and Mal, in the pathogenesis of emphysema has not been studied." (PMID 24205107, 2013). "Next, we determined if imiquimod-induced emphysema has a short-term effect and is TLR7- and MyD88-dependent." (PMID 37963864, 2023). "CS- and imiquimod-induced emphysema is TLR7- and MyD88-dependent." (PMID 37963864, 2023). "Although TLR4 deficiency causes an oxidative imbalance in the lung leading to emphysema in a MyD88-dependent manner, the role of Mal in emphysema has not been studied." (PMID 24205107, 2013).
endometritis (5 papers, 2021 to 2025). An acute or chronic, usually bacterial infectious process affecting the endometrium. "A previous study noted that miR-30a attenuates endometritis in experimental mouse models by targeting MyD88/Nox2 to reduce ROS production." (PMID 37570258, 2023). "We found CT135 activates the NLRP3 inflammasome through TLR2/MyD88 signaling pathway as a pathogenic strategy to evade neutrophil host defense, however, this strategy conjointly caused NLRP3 dependent macrophage-associated endometritis." (PMID 34526512, 2021). "Similarly to the outcomes observed in cellular experiments, the mouse model of endometritis showed that the expression levels of NF-κB pathway-associated proteins, including TLR4, MYD88, and P-NF-κB-p65, were significantly reduced in the treatment group compared to the bacterial challenge group." (PMID 40713896, 2025).
enterocolitis (5 papers, 2010 to 2026). An inflammatory process affecting the small intestine and colon. "There are multiple potential translational implications for the findings that LTα3 and MyD88 contribute to TNF-independent intestinal damage in this model of severe enterocolitis." (PMID 35077396, 2022). "Most importantly, TLR signaling pathways, including MYD88-related and MYD88-non-related pathways, appear to be the principal pathogenic pathways of enterocolitis." (PMID 28515725, 2017).
gastric tumor (5 papers, 2013 to 2020). "We previously reported that the Myd88 gene knockout in gastric tumor mouse model significantly suppressed gastritis and gastric tumor development with the suppression of NF-κB activity, indicating that TLR signaling through NF-κB has a role in tumorigenesis." (PMID 30700829, 2019).
glioblastoma (5 papers, 2017 to 2025). The most malignant astrocytic tumor (WHO grade IV). "Upregulation of the TLR-2, -4, and Myd88 signaling pathways in human glioblastoma U87 cell line has been linked with cell proliferation and invasion." (PMID 34439380, 2021). "Among the six patients with MYD88 c.T778C in plasma, NGS made it possible to distinguish PCNSL from glioblastoma (GBM) in 4 cases." (PMID 28636991, 2017).
Glucose intolerance (5 papers, 2017 to 2024). Glucose intolerance (GI) can be defined as dysglycemia that comprises both prediabetes and diabetes. "Mice with MYD88 deletion were predisposed to glucose intolerance, liver fat accumulation, and inflammation." (PMID 38603936, 2024). "Treatments with either Cxcl1 or IL-1β restored the mature β cell phenotype and rescued MyD88-deficient mice from glucose intolerance, indicating the Cxcl1/IL-1β axis as a potential therapeutic target." (PMID 38885342, 2024). "More precisely, we have reported that mice harboring hepatocyte-specific deletion of MyD88 (Myd88ΔHep) were predisposed to glucose intolerance, liver fat accumulation, and inflammation." (PMID 31039009, 2019). "Intestinal epithelial cell-specific MyD88 deletion decreases fat mass accumulation, body weight gain and glucose intolerance in diet-induced obese mice." (PMID 29163467, 2017). "Similarly, hepatocyte-specific deletion of MyD88 leads to inflammation, glucose intolerance, and hepatic insulin resistance, accompanied by alterations in the microbiota composition." (PMID 29163467, 2017).
HCMV infection (5 papers, 2016 to 2025). "Our data above indicate that UL88 can act in the context of an HCMV infection to reduce MyD88 levels." (PMID 40638072, 2025). "The only antiviral ISG in our screen that we found to be upregulated in the presence of increased levels of MyD88 and HCMV infection was ISG20." (PMID 40638072, 2025). "Furthermore, no viral protein has previously been shown to directly target MyD88 during HCMV infection." (PMID 40638072, 2025). "This study provides evidence that MΦ, which are targets for HCMV infection in vivo, mount high amounts of MyD88-independent IFN-I and thus may contribute to the protection of MyD88 deficient patients." (PMID 27058035, 2016). "IL-1β mRNA is strongly induced following HCMV infection of MyD88-transduced cells, so we investigated whether IL-1β could be responsible for the blockade of HCMV spread by adding IL-1β to our monolayer of MRC-5 cells on d3 post-infection and every 3 days thereafter." (PMID 40638072, 2025). "However, as with infection of MyD88-expressing cells, we observed that the UL88-STOP-mCh HCMV infection, in which MyD88 levels are higher, actually downregulated a number of antiviral ISGs, including IFITM1, IFITM2, IFITM3, MX1, and IFI16 (the nuclear sensor that plays a role in sensing of HCMV)." (PMID 40638072, 2025). "Previous studies have focused on understanding MyD88-dependent and -independent TLR signaling during HCMV infection (10, –, 12) and the role of MyD88 in downstream induction of interferons via activation of NF-κB." (PMID 40638072, 2025). "Previous studies have focused on understanding the MyD88-dependent and -independent TLR signaling during HCMV infection and on MyD88’s role in inducing downstream induction of IFNs (10, –, 12)." (PMID 40638072, 2025).
Helicobacter infection (5 papers, 2013 to 2019). "Helicobacter infection affected the transcriptional profile of more genes in Myd88−/− mice compared to WT mice." (PMID 28201999, 2017). "We have previously reported that Myd88−/− mice do not exhibit abnormal pathology in the absence of Helicobacter infection." (PMID 28201999, 2017).
HIV-1 infection (5 papers, 2015 to 2020). The type species of lentivirus and the etiologic agent of acquired immunodeficiency syndrome (AIDS). "Combined with HIV-1 infection, opiate use resulted in lower expression of MyD88, ISG56, and MxA." (PMID 29026137, 2017). "However, the expression of MyD88 in the Opiate+ HIV+ group and the Opiate− HIV+ group was significantly higher than that in the control group (P < 0.05), indicating that HIV-1 infection promoted the expression of MyD88 in PBMCs." (PMID 29026137, 2017). "From these experiments we conclude that MyD88 activation is insufficient to induce G0 arrest, dephosphorylation of SAMHD1, and blockade of HIV-1 infection." (PMID 32209460, 2020). "Moreover, certain ‘common ISGs’ that were upregulated by HIV-1 infection (IRF7, TRIM25, MYD88, MX2, LGALS9, and SP100) exhibited a strong anti-HIV-1 effect in THP-1 cells." (PMID 30915053, 2019).
kidney injury (5 papers, 2011 to 2025). Trauma to the kidney. "The TLR4/MyD88 pathway has been recognized as a central link in the pathogenic process of systemic inflammation and high-fat exposure-induced kidney injury." (PMID 36230117, 2022).
knee osteoarthritis (5 papers, 2019 to 2025). "Curcumin supplementation can reduce inflammation in knee osteoarthritis rats by blocking the TLR4/MyD88/NF-κB signal pathway." (PMID 35662715, 2022). "Many clinical trials on curcumin supplementation have been conducted on various autoimmune diseases including osteoarthritis, and curcumin can reduce inflammation in knee osteoarthritis rats by blocking TLR4/MyD88/NF-κB signal pathway." (PMID 35662715, 2022).
lymph node metastasis (5 papers, 2012 to 2025). "Combined high TLR4/MyD88 expression significantly associated with lymph node metastasis (p=0.046) and high-grade tumor budding (p=0.002)." (PMID 40703545, 2025). "MyD88 protein expression is positively linked with axillary lymph node metastasis and histological grade." (PMID 38347830, 2024). "The high expression of MyD88 was significantly associated with histological grade (P = 0.0113), lymph node metastasis (P = 0.0001) and liver or lung metastasis (P = 0.0029)." (PMID 22533866, 2012). "Combined TLR4/MyD88 scores ≥5 correlated significantly with lymph node metastasis (42.9% vs 28.3%, p=0.046) and tumor budding grade (p=0.002)." (PMID 40703545, 2025). "Combined TLR4/MyD88 scores ≥5 significantly predicted lymph node metastasis (42.9% vs 28.3%, p=0.046) and high-grade tumor budding (p=0.002)." (PMID 40703545, 2025). "High expression of MyD88 significantly correlates with tumor size, tumor staging, axillary lymph node metastasis, and distant metastasis." (PMID 38347830, 2024). "The protein expression of MyD88 demonstrates a significant positive correlation with tumor size, stage, axillary lymph node metastasis, and distant metastasis." (PMID 38347830, 2024). "Elevated levels of MyD88 expression show a significant correlation with tumor size, staging, axillary lymph node metastasis, and distant metastasis." (PMID 38347830, 2024). "Our study showed that MyD88 overexpression was frequently detected in EOCs with lymph node metastasis and liver or lung metastasis." (PMID 22533866, 2012). "The expression rate of MyD88 is notably higher in samples from patients with axillary lymph node metastasis (59%) compared to those without metastasis (25.6%)." (PMID 38347830, 2024). "Multivariate analyses revealed lymph node metastasis but not MyD88 expression was an independent predictor for patient survival." (PMID 32477927, 2020).
lymphoid neoplasm (5 papers, 2013 to 2025). A neoplasm composed of a lymphocytic cell population which is usually malignant (clonal) by molecular genetic and/or immunophenotypic analysis. "To determine the relevance of the L265P mutation and its association with the clinical characteristics of lymphoid neoplasms, we performed sequencing and mutation analysis on the MYD88 gene in WM and B-cell lymphoma patients." (PMID 24224040, 2013). "Additionally, mutations in the MYD88 gene, particularly the L265P mutation, are commonly found in lymphoid neoplasms and are often present in 93-97% of WM patients, including the patient in this case." (PMID 40109776, 2025).